GAST (gastrin)
Diseases named in the same sentence as GAST in open-access papers (continued):
Sharing a sentence is not in itself a finding about the gene and the disease.
dysplasia (3 papers, 2017 to 2024). A usually neoplastic transformation of the cell, associated with altered architectural tissue patterns. "The results showed that gastrin-17, pepsinogen I, number of lesions, and HP infection were independent risk factors of intestinal metaplasia or dysplasia in CAG patients (p < 0.05)." (PMID 35665336, 2022). "HP infection, pepsinogen I, gastrin-17, and the number of lesions are independent risk factors for intestinal metaplasia or dysplasia in patients with CAG." (PMID 35665336, 2022). "In one study that stratified PPI-treated BE patients by gastrin levels, the highest quartile of gastrin levels was associated with an increased risk of high-grade dysplasia or EAC on biopsy." (PMID 27448962, 2017). "Gastrin stimulated organoid growth in cardia culture, while CCK2R inhibition prevented Barrett's-like esophagus and dysplasia." (PMID 27448962, 2017).
Gastric Metaplasia (3 papers, 2013 to 2025). Intestinal metaplasia of the gastric mucosa is an intermediate precancerous gastric lesion in the gastric cancer cascade from chronic gastritis and atrophy to dysplasia and adenocarcinoma. "Furthermore, mouse gastrin knockout models present with heavily deleterious gastric phenotypes: achlorydic gastric environments with high incidences of gastric metaplasia, bacterial overgrowth and tumours." (PMID 40843895, 2025).
hyperparathyroidism (3 papers, 2012 to 2025). Hyperfunction of the parathyroid glands resulting in the overproduction of parathyroid hormone. "MEN1/ZES occurs in 20–25% of all ZES patients and numerous studies have clearly established the fact that the presence of hyperparathyroidism in these patients (>95% at some point) results in increased BAO, MAO, fasting gastrin levels, and increased resistance to antisecretory drug therapy." (PMID 36900170, 2023).
prostate carcinoma (3 papers, 2016 to 2025). A carcinoma that arises from epithelial cells of the prostate gland. "Gastrin peptide was labeled with AF680 (AF680-gastrin), and imaging was performed to detect breast and prostate cancer lesions." (PMID 27145373, 2016).
type 1 diabetes (3 papers, 2020 to 2026). "However, improved glucose control and neogenesis of functional β‐cell mass have been shown with gastrin treatment, suggesting that Gastrin‐SiO2 microspheres may also have a beneficial effect on type 1 diabetes (T1D), via the gut‐pancreas axis." (PMID 39950948, 2025). "Notably, the hormones GAST and PYY have been reported to be expressed in the developing mouse pancreas and also in hPSC β-cell differentiation protocols, although they are absent from mature β-cells except in type 1 diabetes when GAST becomes upregulated." (PMID 32488111, 2020).
vitamin B12 deficiency (3 papers, 2012 to 2025). A disease characterized by low serum levels of vitamin B12, either inherited or acquired. "In fact, these patients have PCA positivity and raised gastrin; this serological profile, in subjects with iron- or vitamin B12-deficiency anemia, is highly predictive of autoimmune lesion of the stomach mucosa." (PMID 23251219, 2012).
acute pancreatitis (2 papers, 2008 to 2012). An acute inflammatory process that leads to necrosis of the pancreatic parenchyma. "Furthermore, the results suggest that cannabinoid HU210, the CB1/2 receptor agonist, has the therapeutic potential for AGML in acute pancreatitis by attenuating inflammation and restoring gastrin/somatostatin equilibrium, and then decreasing the secretion of gastric acid and pepsin." (PMID 23285225, 2012). "In particular, the increased gastrin, gastric acid output and pepsin jointly play important roles in the pathogenesis of AGML, aggravating the damage of the stomach and triggering vicious cycles during acute pancreatitis." (PMID 23285225, 2012). "When gastrin or somatostatin secretion fails to maintain a basic equilibrium, the surplus pepsin and acid release disproportionally, resulting in damages and dysfunctions of the stomach during acute pancreatitis." (PMID 23285225, 2012).
atherosclerosis (2 papers, 2022 to 2025). A disease characterized by the build-up of fatty material and calcium deposition in the arterial wall resulting in partial or complete occlusion of the arterial lumen. "Other clusters of cytokine signaling in the immune system, gastrin-signaling pathway, lipid and atherosclerosis, apoptosis, pathways in cancer, AGE-RAGE signaling pathway in diabetic complications, and cellular response to nitrogen compound were more related." (PMID 36499711, 2022). "Pathways such as cytokine signaling in immune system, gastrin signaling pathway, lipid and atherosclerosis, apoptosis, pathways in cancer, AGE-RAGE signaling pathway in diabetic complications, and cellular response to nitrogen compound were more clustered." (PMID 36499711, 2022).
autoimmune disease (2 papers, 2020 to 2024). A disorder resulting from loss of function or tissue destruction of an organ or multiple organs, arising from humoral or cellular immune responses of the individual to their own tissue constituents. "We determined the prevalence of gNETs and other autoimmune diseases and analyzed pepsinogen I and II, gastrin-17 serum levels, and H. pylori infection in all patients diagnosed with CAAG at our hospital between 2013 and 2017." (PMID 33094954, 2020). "This study aimed to determine, in CAAG patients, the association of gNET development, the prevalence of autoimmune diseases other than CAAG, the association of autoimmunity, and gNET development with pepsinogen I, II, gastrin-17, and Helicobacter pylori infection analysis." (PMID 33094954, 2020). "This study suggests that a low pepsinogen I/II ratio and high gastrin-17 levels characterize patients with CAAG and gNET and confirms the frequent coexistence of CAAG with other autoimmune diseases." (PMID 33094954, 2020).
Autoimmunity (2 papers, 2020). The occurrence of an immune reaction against the organism's own cells or tissues. "The discrepancy between gastrin values in atrophic gastritis whether due to autoimmunity or H. pylori infection is most probably due to concomitant antral atrophy in the latter condition." (PMID 33266504, 2020).
brain tumors (2 papers, 2013 to 2021). "Recently, receptors for CCK and gastrin were detected in large amounts in the tissues of lung, ovarian, thyroid, and brain tumors." (PMID 24368955, 2013).
colon adenocarcinoma (2 papers, 2002 to 2013). "Recent studies using gastric and colon adenocarcinoma cells confirmed that gastrin is transcriptionally up-regulated by hypoxia, independent of Hif, leading to increased secretion of biologically active forms of gastrin by tumor cells." (PMID 25346875, 2013).
colorectal adenocarcinoma (2 papers, 2002 to 2023). The most common type of colorectal carcinoma. "CDX2 is a transcription factor, a useful marker of intestinal NENs and, because of its association with GI differentiation, it is also found in gastrin-positive pancreatic NENs and colorectal adenocarcinoma." (PMID 37685605, 2023). "The results of these studies suggest the possibility of a functional relationship between gastrin and COX-2 expression and demonstrate that COX-2 selective inhibition is capable of reversing the trophic properties of growth on colorectal adenocarcinoma." (PMID 12189559, 2002).
Crohn disease (2 papers, 2012 to 2017). A gastrointestinal disorder characterized by chronic inflammation involving all layers of the intestinal wall, noncaseating granulomas affecting the intestinal wall and regional lymph nodes, and transmural fibrosis. "Our findings also agree with the hypergastrinemia seen in people with Crohn’s disease whereas they are in contrast with another study that found systemic gastrin concentrations to be normal in Crohn’s disease patients." (PMID 29115998, 2017). "ZES and other infection and Crohn’s disease were also excluded by laboratory findings including the serum gastrin level and clinical symptoms." (PMID 27785190, 2012). "Consistent with our findings is the lack of a correlation between serum gastrin concentration and clinical disease activity seen in people with Crohn’s disease." (PMID 29115998, 2017).
duodenal tumor (2 papers, 2005 to 2017). "Immunostaining of gastrin was strongly positive within the duodenal tumor, but only faintly recognized in the pancreatic tumors." (PMID 28270118, 2017). "This patient had an additional duodenal tumor that was responsible for the gastrin secretion and the clinical diagnosis." (PMID 15691381, 2005). "The patient in this case was first suspected of having MEN1 based on the clinical findings of multiple peptic lesions accompanied by high levels of serum gastrin, calcium, and intact PTH, pancreatic and duodenal tumors suspected for NETs, and a urinary tract stone." (PMID 28270118, 2017).
End-stage renal disease (2 papers, 2015 to 2025). "Patients with uremia, such as secondary to AKI, CKD, or end-stage renal disease (ESRD), have been shown to have a higher incidence of PUD, potentially stemming from increased gastrin levels or alterations in gastric acid secretion." (PMID 40970232, 2025).
esophageal cancer (2 papers, 2022 to 2024). A primary or metastatic malignant neoplasm involving the esophagus. "Since gastrin and its receptors (mediating gastrin effects) are also coexpressed in esophageal cancer and its precursor lesions, they are considered to contribute to the development of esophageal cancers." (PMID 35631344, 2022). "Blocking gastrin suppresses the progress of esophageal carcinoma both in cell line and animal experiments." (PMID 35631344, 2022). "In fact, PPIs cause a physiologically secondary hypergastrinemia, which can reach extremely high plasma gastrin levels in some PPI-treated patients and is proven to be linked with an enhanced risk of high-grade dysplasia or esophageal cancer in a subset of susceptible patients." (PMID 35631344, 2022).
esophageal diseases (2 papers, 2017 to 2025). "Given multiple ulcers in unusual locations and esophagitis being resistant to treatment, serum gastrin levels were sent, and it was found to be 696 pg/mL." (PMID 40291307, 2025).
gastric adenoma (2 papers, 2011 to 2012). A neoplastic polyp that arises from the stomach. "Gastrin knockout (KO) mice are achlorhydric and develop intestinal metaplasia and gastric adenomas over time." (PMID 22992343, 2012). "Gastrin knockout mice are achlorhydric with a tendency for developing antral hyperplasia and gastric adenomas over time." (PMID 21418558, 2011).
gastroenteritis (2 papers, 2019 to 2022). An inflammatory disorder that affects the upper and lower gastrointestinal tract. "Consistent with the mechanism of action of vonoprazan, and similar to PPIs, higher rates of gastroenteritis and increased serum gastrin, pepsinogen I, and pepsinogen II levels were observed after vonoprazan administration." (PMID 31770139, 2019).
Hematemesis (2 papers, 2024 to 2025). The vomiting of blood. "The secretion of gastrin stimulates enterochromaffin-like cells to release histamine and directly promotes gastric acid production by parietal cells; gastrin secretion may correlate with the clinical signs of vomiting and hematemesis reported in dogs with GB NENs." (PMID 41150129, 2025).
hypothyroidism (2 papers, 2021 to 2023). Abnormally low levels of thyroid hormone. "Hypothyroidism caused growth retardation of the mucosa in the abomasum and small intestines, and reduced maltase and DPPIV enzyme activities in the ileum, in association with lower circulating concentrations of cortisol and gastrin." (PMID 36935746, 2023). "Before birth, hypothyroidism may influence the growth and development of the gastrointestinal tract by a variety of mechanisms, and the findings of the present study indicate important interactions between thyroid hormones, cortisol and gastrin in regulating these processes." (PMID 36935746, 2023).
lung carcinoids (2 papers, 2023 to 2024). "Several hormones, including serotonin (84%), pancreatic polypeptide, gastrin, gastrin-releasing peptide, calcitonin, ACTH, and growth-hormone-releasing hormone often show positive immunostaining in lung carcinoids; multiple hormones may be found in the same tumor." (PMID 38001701, 2023).
primary hyperparathyroidism (2 papers, 2021 to 2023). "In addition, primary hyperparathyroidism should have been ruled out as a possible reason for the increase in gastrin levels." (PMID 37008936, 2023).
autonomic neuropathy (1 paper, 2009). An inherited or acquired peripheral neuropathy affecting the autonomic nervous system. "In accordance with earlier studies we found that patients with autonomic neuropathy have significantly higher concentrations of gastrin in plasma." (PMID 19243587, 2009). "In patients with oesophageal dysmotility the basal level of CCK tended to be higher (p = 0.051) and those with autonomic neuropathy had a higher area under the curve (AUC) of gastrin compared to normal subjects (p = 0.007)." (PMID 19243587, 2009). "Reduced postprandial secretion of oxytocin was found in patients with delayed gastric emptying, CCK secretion was increased in patients with oesophageal dysmotility, and gastrin secretion was increased in patients with autonomic neuropathy." (PMID 19243587, 2009). "Although both oxytocin, CCK, gastrin, and vasopressin are involved in postprandial release and motility, the plasma concentrations of these hormones have not been thoroughly examined in relation to dysfunction in GI motility or autonomic neuropathy." (PMID 19243587, 2009). "However, in patients with oesophageal dysmotility the basal concentration of CCK tended to be higher, and in patients with autonomic neuropathy the gastrin concentrations were increased compared to normal subjects." (PMID 19243587, 2009). "Patients with autonomic neuropathy had significantly higher concentrations of gastrin in plasma than patients without neuropathy." (PMID 19243587, 2009). "Earlier studies have reported increased CCK and gastrin concentrations in plasma from diabetics with autonomic neuropathy, whereas patients without neuropathy showed normal concentrations, irrespective of GI function." (PMID 19243587, 2009).
Cachexia (1 paper, 2023). Severe weight loss, wasting of muscle, loss of appetite, and general debility related to a chronic disease. "Gastrin levels have been reported to be 50% higher in cancer patients with cachexia." (PMID 37533569, 2023).
Chronic constipation (1 paper, 2023). Constipation for longer than three months with fewer than 3 bowel movements per week, straining, lumpy or hard stools, and a sensation of anorectal obstruction or incomplete defecation. "Moreover, ginger has been reported to enhance circulating levels of gastrin, which its release seems to be impaired in patients with chronic constipation." (PMID 37891539, 2023).
chronic intestinal pseudo-obstruction (1 paper, 2013). "Gonadotropin-releasing hormone has been shown to inhibit the release of gastric secretion and gastrin release in dog, and to stimulate motor function in the gastrointestinal tract in female rats and in a patient suffering from chronic intestinal pseudo-obstruction." (PMID 23958111, 2013).
co-infection (1 paper, 2015). "In particular we aimed to identify whether HIV infection alone or as a co-infection with H. pylori was implicated in causing hypochlorhydria, and to understand the mechanism by studying histological changes and gastrin levels." (PMID 26244370, 2015). "H. pylori infection alone was more likely to lead to antral gastritis (which might not be expected to cause a significant increase in serum gastrin concentrations), while pangastritis (more likely to cause increased serum gastrin concentrations) was associated with co-infection with HIV." (PMID 26244370, 2015).
COVID-19 (1 paper, 2023). A disease caused by infection with severe acute respiratory syndrome coronavirus 2. "Interestingly, an in silico modeling study examining molecular dynamics suggested that pentagastrin, a synthetic polypeptide that has effects like gastrin when given parenterally, could be a viable drug for COVID-19." (PMID 37759668, 2023).
cyst (1 paper, 2008). A sac-like closed membranous structure that may be empty or contain fluid or amorphous material. "The cyst mucosa showed numerous endocrine cells located in the gastric glands (gastrin, somatostatin and serotonin), the duodenal glands (serotonin, somatostatin, secretin, gastrin and bombesin) and the small-intestinal glands (serotonin, somatostatin, secretin and bombesin)." (PMID 18498655, 2008).
dependent (1 paper, 2013). "The reduction in abundances, plasma CgA, and tumour number and size by netazepide show that type 1 NETs are gastrin-dependent tumours." (PMID 24098507, 2013).
fibrosis (1 paper, 2021). the formation of excess fibrous connective tissue in an organ or tissue in a reparative or reactive process. "Masson's trichrome staining showed that gastrin treatment decreased myocardial fibrosis; moreover, angiogenesis was increased by gastrin, as indicated by CD31 staining." (PMID 34349170, 2021).
gastric gastrinomas (1 paper, 2015). "In summary, patients with gastric gastrinomas usually have older age, higher gastrin level, more subcentimeter tumor size, and significantly lower tumor grading." (PMID 26077245, 2015). "Comparing with those of hepatic-pancreatic-biliary origins, gastric gastrinomas had significantly higher gastrin levels but smaller tumor size, lower ki-67 proliferation index, and more well-differentiated tumors (G1)." (PMID 26077245, 2015). "Patients with gastric gastrinomas had older age, higher levels of gastrin, seemingly smaller tumor size (p = 0.024, 0.030, and 0.065, respectively), and usually lower grade in differentiation (p = 0.035)." (PMID 26077245, 2015).
gastric varices (1 paper, 2019). "This explains why the gastrin level was significantly higher in H. pylori positive patients with bleeding gastric varices compared to those without bleeding (78.34 ± 35.2 and 51.15 ± 46.92 pg/mL, respectively) (P = 0.0380)." (PMID 30881448, 2019).
gastrointestinal carcinoma (1 paper, 2020). "Accumulating evidence showed that gastrin signaling via CCK2R stimulates the growth of gastrointestinal cancer cells in vitro and in vivo, indicating blockade of CCK2R pathway might present a promising strategy for the treatment of gastrointestinal carcinoma." (PMID 32210918, 2020).
Gastrointestinal dysmotility (1 paper, 2023). Abnormal intestinal contractions, such as spasms and intestinal paralysis, related to the loss of the ability of the gut to coordinate muscular activity because of endogenous or exogenous causes. "Additionally, the increase in gastrin concentration after a meal was correlated with low PDP, APSWC and normogastria, which are indicators of gastrointestinal dysmotility." (PMID 37296188, 2023).
gastrointestinal stromal tumor (1 paper, 2017). "The functional role of PKCθ in ICC is not known, but a recent study reported that PKCθ protein is hyper-activated in gastrin induced gastrointestinal stromal tumors (GIST) via gastrin and cholecystokinin receptor CCK2R, suggesting that the protein promotes ICC proliferation and GIST tumorigenesis." (PMID 28426719, 2017).
gastroparesis (1 paper, 2021). Paralysis of the muscles of the stomach wall resulting in delayed emptying of the gastric contents into the small intestine. "the environment of G cells in the residual stomach are changed, leading to increased gastrin secretion.According to the onset time, postsurgical gastroparesis can be divided into acute and chronic." (PMID 32880749, 2021).
Hashimoto’s disease (1 paper, 2021). "We determined that the patient had AIG because she also had Hashimoto’s disease, the PCA titer was high, the serum gastrin level was slightly increased, and inflammation was observed only in the gastric body on the endoscopic images." (PMID 33566307, 2021).